RFPL4AL1 (ret finger protein like 4A like 1)
Synonyms: RNF210B
Tractability: PROTAC: ubiquitination databases record sites on it.
Gene: Protein-coding gene on chromosome 19 (55,769,118 to 55,773,420, forward strand). Ensembl gene ENSG00000229292.
Subcellular location (Human Protein Atlas): Centrosome; Cytosol
Gene Ontology:
Molecular function: ubiquitin protein ligase activity
Biological process: innate immune response; regulation of gene expression
Cellular component: cytoplasm
Genetic constraint (gnomAD): Loss-of-function variants: 2 observed, 4.68 expected, observed/expected ratio (o/e) 0.43, 90% interval 0.17 to 1.32. That is too few expected variants to judge how well the gene tolerates losing a copy. Missense variants: 56 observed, 195.17 expected, observed/expected ratio (o/e) 0.29, 90% interval 0.23 to 0.36. Synonymous variants: 25 observed, 72.47 expected, observed/expected ratio (o/e) 0.34, 90% interval 0.25 to 0.48.
Homologues: Orthologues: macaque RFPL4A (87% identical), dog RFPL4A (61% identical), mouse Rfpl4 (54% identical). Paralogues in human: RFPL4A (99% identical), RFPL1 (57% identical), RFPL3 (57% identical), RFPL2 (55% identical), RFPL4B (30% identical), RNF135 (23% identical), SPRYD4 (11% identical), CD274 (7% identical), RNF152 (7% identical), CD86 (7% identical), PDCD1LG2 (6% identical), CD80 (5% identical).